KRAS (KRas proto-oncogene, GTPase)
Diseases named in the same sentence as KRAS in open-access papers (continued):
Sharing a sentence is not in itself a finding about the gene and the disease.
cancer (continued). "Clinical responses to anlotinib combination treatment in KRAS-mutant patients have been reported in multiple cancer types, especially NSCLC, providing evidence for the potential application of our combined strategy." (PMID 40316534, 2025). "Glecirasib potently and selectively inhibits KRAS G12C and reduces ERK and AKT phosphorylation in KRAS G12C–mutant cancer cells, further inducing cell-cycle arrest and apoptosis." (PMID 40304209, 2025). "The vast majority of mutations cluster at hotspot codons 12, 13, and 61, accounting for about 85% of KRAS alterations in human cancers." (PMID 41514544, 2025). "This study brings forward a novel therapeutic concept for KRAS WT–amplified cancers and provides the preclinical rationale for the use of pan-KRAS inhibitors to treat patients with cancers with KRAS WT amplifications (CN > 7)." (PMID 39711431, 2025). "A previous study has reported that concurrent inhibition of SOS1 and KRAS synergistically suppresses the proliferation of KRAS-mutant cancer cells." (PMID 39437162, 2025). "In one paper by Solanki and colleagues, NSCLCs with an epithelial gene signature tended to upregulate ERBB2/3 signaling in response to KRAS repression, while cancers with a mesenchymal signature relied more on FGFR1 and AXL signaling." (PMID 40940900, 2025). "Another study by our group demonstrated that NRP1 knockdown in cancer cells depends on the genetic status of KRAS." (PMID 40277760, 2025). "This review explores the complex function of KRAS in cancer development, highlighting its influence on immune regulation and resistance to therapy." (PMID 40075634, 2025). "Mutations in the Kirsten rat sarcoma viral oncogene homolog (KRAS) GTPase protein are among the most prevalent in cancer." (PMID 40662822, 2025). "Crosstalk between the Hippo/YAP and KRAS pathways is vital for cancer development, progression, and resistance to therapy." (PMID 40895190, 2025). "The release of EVs containing KRAS is facilitated by autophagy-dependent ferroptosis in cancer cells." (PMID 39810420, 2025). "The results of a GST pull-down assay confirmed that 150 μM RBP treatment significantly inhibited RAS–RAF binding in KRAS G13D mutant cancer cells and suppressed ERK1/2 phosphorylation." (PMID 40236954, 2025). "Mutant KRAS induces aberrant DNA methylation patterns, silencing tumor suppressor genes and activation of oncogenes, thereby contributing to cancer progression." (PMID 39806421, 2025). "For example, cancer cells can evade KRAS G12C inhibitors through activation of the YAP pathway or via epithelial‐to‐mesenchymal transition (EMT) processes." (PMID 41020040, 2025). "The ability of these molecules to target multiple KRAS mutants—including G12D, G12C, and G12V—suggests their potential as pan-KRAS inhibitors, addressing a critical gap in targeted cancer therapies." (PMID 40360486, 2025). "To further support these findings, we examined REGγ protein expression in different KRAS-mutant cancer cell lines." (PMID 40091835, 2025). "A preclinical study explores the development of novel Son of sevenless homolog 1 (SOS1) degraders using PROTAC technology to target KRAS‐driven cancers." (PMID 39898116, 2025). "Inhibitors targeting PI3K (e.g., Alpelisib), AKT (e.g., Ipatasertib), mTOR (e.g., Everolimus), are frequently used in combination with other drugs to target KRAS-driven cancers." (PMID 39806421, 2025). "On the other hand, clinical trials revealed the acquired resistance to the inhibitors, leading to their restricted efficacy only in a small subset of KRAS mutant cancers." (PMID 40244134, 2025). "Studies of cell lines with KRAS G12C mutations generated from ARS-1610 and AMG510 and their effects on cancer cells have shown that downstream effectors are still activated and that the levels of active KRAS and HRAS wild-type proteins are increased." (PMID 40597785, 2025).
cancer (continued). "Despite advances in the development of direct KRAS inhibitors, KRAS-mutant cancers continue to exhibit resistance to the currently available therapies." (PMID 40091835, 2025). "This section explores how KRAS inhibitors have been developed to target G12C and other mutant forms of KRAS in specific types of cancer." (PMID 39820726, 2025). "Continuous suppression of the RAS pathway and improved effectiveness of KRAS inhibitors in KRASG12C-mutant cancer models were achieved through vertical pathway inhibition." (PMID 39437162, 2025). "These proteins have previously been linked to EGFR or KRAS mutations and are known as prognostic markers for NSCLC and other cancers." (PMID 40621945, 2025). "More recently, the type of feedback reactivation of survival pathways in cancer cells upon KRAS G12C inhibition has been correlated with the transcriptional features." (PMID 40940900, 2025). "Significantly, this editing tool delivered by LNPs has demonstrated minimal off-target effects in organoids and mouse models, thus holding significant therapeutic potentials for KRAS-mutant cancer treatment." (PMID 39820726, 2025). "Understanding these differences is essential for selecting the most suitable therapeutic strategy in the context of KRAS-driven cancers." (PMID 39820726, 2025). "Traditional prognostic biomarkers such as CEA, CA19-9, and KRAS have been utilized to predict the likely course of disease progression in cancer, allowing physicians to personalize their patients’ treatments based on their cellular characteristics." (PMID 40940822, 2025). "PP6 has been found to limit the growth of KRAS- and Braf-mutant cancer models thus exhibiting tumor-suppressing activity." (PMID 40862737, 2025). "The applications of miRNAs, has shown promising result in targeting mutant KRAS inhibition in several types of cancers." (PMID 39820726, 2025). "PMP tumors had significant upregulation of pathways associated with cancer development and progression that included epithelial mesenchymal transition (EMT), JAK-STAT and KRAS signaling." (PMID 40018643, 2025). "Current evidence highlights the immune microenvironment as a key factor in overcoming the therapeutic challenges of KRAS-mutant cancers." (PMID 40611261, 2025). "This points to the importance of properly selecting the right treatment or combination basing on the molecular features of each KRAS G12C-mutant cancer." (PMID 40940900, 2025). "LY3214996 was found to be well-tolerated and worked well in combined modality settings in xenograft models of KRAS-mutant NSCLC and colorectal cancer, and has therefore been advanced into human clinical trials in cancers of RAS mutations." (PMID 40943615, 2025). "Based on these findings, in this study, we investigated the anticancer potential of RBP by applying it to specific KRAS-mutant cancer cells." (PMID 40236954, 2025). "The pro/anti-angiogenic function of NRP1 shows a novel pathway in cancer metastasis mediated by KRAS and TGF-β signaling through NRP1." (PMID 40277760, 2025). "Using our new biosensors and biochemical assays, we performed single-cell signaling analyses to identify and characterize a subpopulation of KRas-G12C-addicted cancer cells that evade several Ras-G12C inhibitors." (PMID 39103633, 2025). "The Hippo/YAP and KRAS pathways are central regulators of cell growth, survival, and cancer progression." (PMID 40895190, 2025). "α-KG and oxaloacetate support amino acid synthesis (e.g., glutamate, glutamine), while aspartate drives nucleotide production, critical for DNA replication in KRAS-driven cancers." (PMID 40734168, 2025).
cancer (continued). "RAS was initially identified for its oncogenic properties, with KRAS mutations constituting the most prevalent, comprising 85% of all RAS oncogenic mutations and affecting 12% of all cancer patients." (PMID 40611261, 2025). "KRAS mutations are predominant in many cancers, including PDAC, NSCLC, and CRC, and alongside the FDA-approved KRAS G12C inhibitor, sotorasib, acquired clinical resistance." (PMID 40756996, 2025). "This review provides a comprehensive overview of current knowledge, spanning biological mechanisms, translational research, and clinical advances related to KRAS G12C-mutant cancers." (PMID 40940900, 2025). "This review summarizes the immune microenvironment in KRAS-mutant cancers and the latest advances in immunotherapy, emphasizing subtype heterogeneity and potential future directions in treatment." (PMID 40611261, 2025). "We investigated the frequency of RAS mutations (KRAS, NRAS, HRAS) in different cancer types using the C-CAT database, a Japanese national cancer genome database." (PMID 40970755, 2025). "Overall, our in vivo findings corroborate the in vitro results, showing for the first time that direct pharmacologic inhibition of WT KRAS suppresses the growth of cancers carrying KRAS WT amplifications (CN > 7)." (PMID 39711431, 2025). "In summary, the current clinical trials related to targeted cancer metabolism encompass a diverse array of drugs and targets, including KRAS G12C, HER2, Trop-2, PD-1/PD-L1, TIGIT, and NTRK fusion genes." (PMID 39744225, 2025). "In our study, we investigated the differences between wild-type and mutant KRAS isogenic cells through proteomic analysis, identifying REGγ as a key protein whose expression is markedly altered in KRAS-mutant cancer cells." (PMID 40091835, 2025). "The treatment involved intravenous administration once weekly for four weeks, repeated every six weeks, with longer treatment durations for patients with KRAS mutant cancers." (PMID 40390497, 2025). "In particular, HMucBOT-2 demonstrated copy number gains in chromosomes 5 and 12 where KRAS, KMT2D, and CLIP1 are located and have been associated with cancer transformation." (PMID 40427213, 2025). "Taken together, our findings highlight COA4 as a critical target for the treatment of KRAS mutant‐driven cancer metastasis." (PMID 40936169, 2025). "KRAS is a part of the RAS family, which is regularly mutated, and it is suggested to be the oncogenic gene that prevalently drives human malignancies/cancers." (PMID 40075634, 2025). "Activating KRAS mutations are a specific subset of MAPK signaling disruptions that lead to tumorigenesis in PaCa and other cancer types." (PMID 40862737, 2025). "The development and clinical success of G12C mutant-specific KRAS inhibitors was a landmark achievement in anti-cancer drug development, as the oncogenic KRAS protein had long been considered an intractable therapeutic target." (PMID 40890297, 2025). "Recently, the development of KRAS G12C inhibitors (e.g., sotorasib, adagrasib) has paved the way for major breakthroughs in the treatment of KRAS-driven cancers." (PMID 41514544, 2025).
cancer (continued). "Targeting RBM39/DCAF15, a key regulator of KRAS mRNA splicing, has demonstrated promising potential in inhibiting cancer stem cells." (PMID 40563429, 2025). "By binding to the catalytic domain of SOS1, BI-346 blocks its interaction with KRAS, reducing the formation of GTP-bound RAS and cellular proliferation in various types of KRAS-driven cancers." (PMID 40362343, 2025). "Given that FAK activates the PI3K-Akt pathway, our observation is consistent with previous studies that have demonstrated KRAS-mutant cancer cells become more sensitive to PI3K inhibition following KRAS knockdown or inhibition." (PMID 41322195, 2025). "So far, miRNAs such as miRNA let-7, miR-18a-3p, miR-29b-3p, miR-30b, miR-126-5p, miR-143-3p,miR-143-3p and miR-155-5p have been identified as KRAS regulators in different types of cancers." (PMID 39820726, 2025). "Previous research has found that KRAS is upregulated in a variety of human cancers and that this upregulation contributes to tumorigenesis." (PMID 40390765, 2025). "RLY01 exerted potent antitumor effects on KRAS-driven cancers by modulating cell proliferation and apoptosis both in vitro and in vivo." (PMID 40091835, 2025). "For decades KRAS was considered undruggable, but recent advances have produced selective KRAS inhibitors, creating new opportunities for personalized cancer treatment." (PMID 41514544, 2025). "Meta-analyses have reported that approximately 19% of all cancer patients harbor RAS mutations, with KRAS mutations accounting for 75% of these cases." (PMID 41170373, 2025). "TANK-binding kinase 1 (TBK1) is essential for oncogenic KRAS-induced cell transformation and maintains the survival of KRAS-dependent cancer cells." (PMID 41184283, 2025). "Autophagy, the cellular process of recycling organelles and proteins, is an established pathway reovirus utilizes to kill KRAS-mut cancer cells." (PMID 40526688, 2025). "While our study focused on NSCLC, the applicability of this combination strategy to other KRAS-G12C mutant cancers requires further investigation." (PMID 40316534, 2025). "It has also been reported that SOS1 PROTAC exhibits potent antitumor activity in KRAS-mutant cancers." (PMID 39437162, 2025). "While KRAS G12C inhibitors offer new hope for patients with previously difficult-to-treat cancers, the rapid co-evolution of the biological and clinical scenario creates new challenges." (PMID 40940900, 2025). "Hypoxia inducible factor 1 (H1F-1a) is upregulated by the KRAS signalling pathway, allowing cancer cells to adapt to hypoxia." (PMID 40567499, 2025). "Due to this expression, changes are observed in the morphology of the cells along with increased proliferation, similar to the Kirsten Rat Sarcoma viral oncogene homolog (KRAS) V12 mutant present in other cancer types." (PMID 41246330, 2025). "Altogether, inhibiting KRas appears to be a promising strategyto provide a therapeutic window for KRas-driven cancers." (PMID 40553022, 2025). "Here, we use the pan-KRAS inhibitors BI-2865 and BI-2493 to show an antiproliferative response in a range of WT KRAS–amplified [copy number (CN) > 7] preclinical cancer models, confirming that amplification represents a KRAS oncogenic driver alteration." (PMID 39711431, 2025). "Molecular docking revealed stronginteractions of sarcorine C and salonine C with key cancer-associatedproteins (CDK2, KRAS, CYP17A1, Bcl-2, MMP-2, and NOS)." (PMID 41141772, 2025). "We propose that owing to its retained hydrolytic activity and dependency on upstream activators, KRAS WT–amplified cancers remain sensitive to KRAS “OFF” inhibitors." (PMID 39711431, 2025).
cancer (continued). "Targeting KRAS has been a significant challenge in cancer therapy due to its structure, which lacks easily druggable pockets, making it difficult for conventional small molecules to bind effectively." (PMID 39806421, 2025). "In a Phase I clinical trial with doses ranging from 50 to 200 mg twice daily, LY3537982 showed a promising safety profile for KRAS G12C—related cancer." (PMID 39820726, 2025). "Trametinib is reported to be effective in combination with other drugs in KRAS‐mutant cancers, and trametinib used in this study is a clinically applicable dose." (PMID 39400496, 2025). "Collectively, these data revealed that SIAIS560255 exerts significant inhibitory effects on KRAS-driven cancer cells." (PMID 39437162, 2025). "The therapeutic quest to treat KRAS G12C-mutant cancers with selective inhibitors started less than ten years ago has already provided multiple advancements towards a progressive optimization based on clinical and biological breakthroughs." (PMID 40940900, 2025). "Drug resistance in KRAS-dependent CRC patients remains one of the cancer field’s most persistent challenges." (PMID 40634495, 2025). "Our analysis shows that certain cancers are clearly biased by key signatures (e.g., KRAS G12 substitutions)." (PMID 41465353, 2025). "This lack of mechanistic insights presents a limitation to the development of effective therapeutic strategies to overcome cancer resistance to KRAS-targeted drugs, and calls for further study in this important area." (PMID 41391757, 2025). "Divarasib’s entry into the landscape of KRAS G12C inhibitors marks an interesting advancement in cancer therapy, particularly for tumors that are resistant to conventional treatments." (PMID 40940900, 2025). "The common genes that exhibited concordant expression trends in CRC and PDAC KRAS‐mutant cells compared with their corresponding KRAS‐WT cancer cell lines were MUC1, ITGA3, and PHLDA." (PMID 40013338, 2025). "The research above indicated that particular inhibitors targeting KRAS (G12C) in cancer cells fruitfully led to the transformation to an immunocompetent from an immunosuppressive TME." (PMID 40075634, 2025). "Broad activity was observed across a wide range of KRAS-altered cancer cell lines, in agreement with previous results." (PMID 39711431, 2025). "Our aim was to develop an allele-specific CRISPR targeting strategy for pathogenic DNA sequences that contains cancer-related EGFR L858R and KRAS G12V mutations." (PMID 41301194, 2025). "KRAS WT–amplified cancer cell lines, with a copy number >7, were identified as the most sensitive, across cell lines with any KRAS alterations, to our pan-KRAS inhibitors." (PMID 39711431, 2025). "The KRAS DNA G4 has been identified as a key modulator of gene expression, and stabilizing or destabilizing this structure can significantly impact cancer progression." (PMID 40333779, 2025). "In vitro experiments confirmed the expected changes in the expression of most genes in the CRC‐MT and ‐KRAS‐WT cancer cell lines." (PMID 40013338, 2025). "The development and clinical success of KRASG12C inhibitors was a landmark achievement in anti-cancer drug development, as oncogenic KRAS had long been considered an intractable therapeutic target." (PMID 40890297, 2025). "KRAS mutations are cancer type-specific, with 98% of PDAC KRAS mutations occurring at codon 12, codon 13 (G13), or codon 61 (Q61)." (PMID 40002297, 2025). "Although this approach is mechanistically sound, the clinical efficacy of FTIs in KRAS-mutant cancers, including MOCs, has been limited." (PMID 40862711, 2025). "In PDAC, KRAS inhibitors can partially remodel the microenvironment by reducing myeloid cell accumulation, increasing CD8+ T-cell infiltration, and reprogramming cancer-associated fibroblasts." (PMID 41170373, 2025).